LACTB (lactamase beta)
Diseases named in the same sentence as LACTB in open-access papers (continued):
Sharing a sentence is not in itself a finding about the gene and the disease.
cancer (continued). "This review provides a comprehensive analysis of expression level, structure–function relationships, and the diverse roles of LACTB in oncogenesis, underscoring its promise as a focal point for precision cancer therapies." (PMID 39941048, 2025). "Studies have shown that modulating LACTB expression in cancer cells can positively impact the EMT process, encourage cell cycle arrest, and induce cancer cell death via autophagy, apoptosis, and ferroptosis." (PMID 39941048, 2025). "The maintenance of the filament structure directly impacts both enzymatic activity and the regulation of mitochondrial cristae morphology, highlighting the important role of LACTB filament in cancer." (PMID 39941048, 2025). "Subsequent sections explore the differential expression of LACTB in various cancer types, with the aim to elucidate its roles in tumorigenesis and cancer progression." (PMID 39941048, 2025). "We showed that Slug down-regulation led to impairment of cancer cell proliferation and migration capacities, thus mimicking the effect of LACTB induction on cancer cells." (PMID 36375842, 2023). "Current research findings suggest that LACTB can modulate the migration and invasion capacity of cancer cells in multiple solid tumors, although it has been observed to exhibit inhibitory effects in some tumors and oncogenic effects in others." (PMID 38149985, 2023). "However, the detailed mechanism underlying the LACTB-induced cancer cell death is largely unknown." (PMID 36282364, 2023). "The expression of LACTB in cancer cells significantly reduced their proliferation rate, whereas it had minimal effect on the growth of non-tumorigenic cells." (PMID 36375842, 2023). "Since the presence of ROS within cells is one of the main causative agents of the appearance of DNA damage we examined if cancer cells had an increase in ROS production upon LACTB induction." (PMID 36282364, 2023). "LACTB was found to inhibit cancer cell proliferation in numerous tissues through modulation of cancer cell death or cancer cell differentiation/EMT, both processes being cell-type-specific." (PMID 36282364, 2023). "The physiological function and antiproliferative mechanism of LACTB are incompletely understood, although induced LACTB expression in cancer cells was found to affect mitochondrial phospholipid metabolism." (PMID 36356032, 2022). "Herein, this article focuses on the comprehensive impacts of LACTB on cancers and attends to undermine the structural basis for the catalytic activity of LACTB to elucidate its role in cancer events." (PMID 36078157, 2022). "This perspective provides novel insights for LACTB as a metabolic regulator with potential to develop targeted cancer therapies or neoadjuvant therapeutic interventions." (PMID 36078157, 2022). "Recent results from studies on LACTB expression in different cancer forms have yielded some support for this interpretation." (PMID 35626737, 2022). "Given LACTB’s roles in cancer pathogenesis and therapeutic responses, understanding about its regulatory mechanisms is critical for developing precise and effective LACTB-targeted cancer therapeutics." (PMID 36078157, 2022). "Hence, mutation may be another angle in studying LACTB’s role in cancer." (PMID 36078157, 2022). "This study uncovers an important aspect of how LACTB functions as a tumor suppressor and provides a foundation for future cancer research and drug therapy with LACTB as a target." (PMID 36534696, 2022). "Our results elucidate that LACTB is involved in the development of cancer, and that high LACTB expression in patients with PAAD can predict a poor prognosis." (PMID 33507917, 2021). "LACTB is downregulated in cancer cells through multiple mechanisms, including micro-RNA-mediated translational inhibition, promoter methylation, and histone acetylation." (PMID 34361072, 2021). "Our results showed a positive correlation between mRNA expression and LACTB in most normal and cancer tissues." (PMID 33507917, 2021).
cancer (continued). "The overexpression of LACTB negatively impacts the growth of both breast cancer and hepatocellular carcinoma cells by modulating lipid metabolism to promote cancer cell differentiation." (PMID 34361072, 2021). "Our results suggest that LACTB is involved in cancer progression and that high LACTB expression in PAAD patients predicts poor prognosis." (PMID 33507917, 2021). "Through TCGA datasets and Pan‐cancer TMA analysis, we confirmed that both LACTB mRNA and protein were frequently dysregulated expression in cancers." (PMID 29790671, 2018). "In view of the expression difference in mRNA and protein, we further analyzed the expression difference of LACTB protein in Pan‐cancer TMA." (PMID 29790671, 2018). "However, in specific cancers, LACTB exhibits oncogenic properties, significantly contributing to malignancy." (PMID 39941048, 2025). "Notably, analysis of the two cell lines revealed that in HGC-27, a poorly differentiated cancer cell line, the expression of LACTB protein is, similar to most other cancers, significantly lower than that in normal gastric mucosal tissues." (PMID 39941048, 2025). "Collectively, these studies establish LACTB as a versatile regulator of cancer cell death pathways." (PMID 39941048, 2025). "In addition to transcriptional regulation, research on LACTB expression in various cancers has revealed that LACTB mRNA translation is also finely regulated within cancer tissues." (PMID 39941048, 2025). "Moreover, upregulating LACTB induces mitochondrial dysfunction in cancer cells, ultimately triggering ferroptosis, an iron-dependent form of cell death." (PMID 39941048, 2025). "Overexpression of LACTB inhibits cancer cell proliferation, migration, and invasion." (PMID 39047638, 2024). "As we observed, over‐expression of wt‐LACTB suppressed the proliferation of cancer cells." (PMID 39324579, 2024). "Moreover, concomitantly, there was also a significant increase in cancer cells in G1-phase upon LACTB induction, indicative of their cell cycle arrest." (PMID 36375842, 2023). "LACTB can regulate mitochondrial lipid metabolism through mitochondrial phosphatidylserine decarboxylase, thus modulating the proliferation and differentiation of cancer cells." (PMID 38149985, 2023). "More specifically, the upstream signaling, LACTB promotor activity, alternative splicing, microRNA (miRNA) regulation, and PTMs may play decisive roles in the expression and catalytic activity of LACTB in cancer tissues." (PMID 36078157, 2022). "Hence, targeting lipid metabolism by combing traditional chemotherapeutic drugs is a promising strategy to overcome drug resistance in cancer, and LACTB is an effective lipid metabolic switch in chemotherapeutic responses." (PMID 36078157, 2022). "The serine protease domain of LACTB has been proposed to participate in proteolytic signaling cascades, such as mitochondria-mediated apoptosis; furthermore, LACTB participates in the PS metabolism, manifesting its involvement in immunoregulation in cancer." (PMID 36078157, 2022). "In this way, the human LACTB (hLACTB) filament formation may have played a critical role in cancer development and progression as well as anticancer therapeutic responses." (PMID 36078157, 2022). "This discrepancy suggests that the real roles of LACTB vary in different cancer types and that other unreported mechanisms may be involved in the effects of LACTB in PAAD." (PMID 33507917, 2021). "However, inconsistent with our research, low LACTB is closely related to the poor prognosis of many cancers." (PMID 33507917, 2021). "In addition, CDC20, CDK4, MCM6, MAD2L1, MCM2 and MCM5 were leading genes intersecting in these four pathways, and a positive correlation between mRNA expression and LACTB was observed in most normal and cancer tissues." (PMID 33507917, 2021). "In this study, we demonstrated that LACTB was frequently dysregulated in cancers." (PMID 29790671, 2018).
cancer (continued). "Hence, LACTB may exhibit a pro-inflammatory effect in the macrophage-based anticancer therapy, and the correlations of LACTB expression with macrophage infiltration level are visualized in various cancers." (PMID 36078157, 2022). "Moreover, the alkaline pH, one of the unique mitochondrial characteristics in pathological cancers, may have facilitated the cleavage activity of LACTB." (PMID 36078157, 2022). "Elucidating the biochemical and cell biological function of LACTB may hence lead to useful new insights into the regulation of the lipid metabolism and may enlighten on how aberrations in lipid metabolism contribute to the development of cancer, and possibly other disorders." (PMID 35626737, 2022). "Because the expression of LACTB mRNA was higher in cancer tissues than in normal tissues in PAAD patients, the relationship between LACTB mRNA and clinical characteristics must be further explored." (PMID 33507917, 2021). "Moreover, studies on LACTB in cancer revealed that LACTB expression and its enzymatic activity effectively suppress PISD protein levels, thereby limiting the excessive synthesis and accumulation of PE in cancer cell mitochondria." (PMID 39941048, 2025). "Through proliferation experiments, we tested the influence of LACTB in cancer cell lines and non-tumorigenic cell lines (immortalized primary cells and FTSECs) up to 12 d of induction of LACTB." (PMID 36375842, 2023). "In contrast to cancer cells, LACTB expression does not lead to Slug down-regulation in non-tumorigenic cells." (PMID 36375842, 2023). "Re-expression of LACTB negatively effects the growth of cancer cells but not of non-tumorigenic cells." (PMID 36375842, 2023). "Our results showed that in contrast to cancer cells, LACTB expression does not lead to down-regulation of the Slug protein in non-tumorigenic cells." (PMID 36375842, 2023). "The signaling pathways that enable LACTB to suppress proliferation of some cancers but not others will be the subject of future investigations." (PMID 28785375, 2017). "This suggests that LACTB appears to facilitate continuous cell cycle progression and unchecked cell cycle progression, thus enabling sustained proliferation and potentially aiding cancer development rather than suppressing it." (PMID 39941048, 2025). "However, LACTB expression is elevated in the NPC tissue compared to the non-cancer nasopharyngeal tissue, which is correlated with malignant behaviors and poorer survival in NPC." (PMID 36078157, 2022). "We did not determine whether miR‐374a/LACTB axis regulates fatty acid metabolism in BRCA cancer due to the limit of experimental instrument." (PMID 29790671, 2018). "We expressed doxycycline-inducible Slug in two cancer cell lines (EFO27 and PEO4) and performed the Western blot analysis to examine its protein levels in the presence and absence of LACTB." (PMID 36375842, 2023). "Supplementing the tissue culture medium of LACTB-induced MCF7-RAS cancer cells with 20 μM LPE (but not PE) increased proliferation, in essence partially reversing the growth inhibitory effect of LACTB expression." (PMID 28785375, 2017). "Overall, LACTB decreases PISD and hence PE/LPE in some but not all cancers and fails to do this in nontumorigenic cell lines." (PMID 28785375, 2017). "Additionally, IMS serine protease LACTB, leading to PSD degradation, changes mitochondrial lipid metabolism in certain cancer cells, but not in nontumourigenic differentiated cells." (PMID 33794068, 2021).
LACTB also shares sentences with these, for which no sentence is quoted: lymph node metastasis (1 paper); multiple myeloma (1); ovary adenocarcinomas (1); serous adenocarcinoma (1); uveal melanoma (1).